ICAM1 (intercellular adhesion molecule 1)
Diseases named in the same sentence as ICAM1 in open-access papers (continued):
Sharing a sentence is not in itself a finding about the gene and the disease.
tumor (continued). "Moreover, STING signaling enhances the expression of adhesion molecules such as E-selectin, vascular cell adhesion molecule-1 (VCAM-1), and intercellular adhesion molecule-1 (ICAM-1) on tumor endothelial cells, thereby facilitating T cell extravasation." (PMID 41204180, 2025). "However, in blood, we observed the same trend again as in tumor where high VCAM-1 and ICAM-1 levels showed a significant association with a low-medium SCS." (PMID 40652770, 2025). "Similarly, IL-8 attracts neutrophils and upregulates the expression of Mac-1 on their surface, enhancing their anti-shear adhesion ability with tumor cells expressing ICAM-1." (PMID 40528159, 2025). "In tumor, high levels of VEGF, VCAM-1 and ICAM-1 were significantly associated with low-medium SCS." (PMID 40652770, 2025). "Normally, ICAM-1 expression is low on resting vascular endothelial cells but increases during inflammatory and immune responses, aiding in the clearance of foreign antigens and tumor cells." (PMID 39910824, 2025). "Next, we evaluated the antitumor effects of ICAM‐1‐Dxd plus B7‐H3‐CD3 in PDX TNBC tumor models." (PMID 39996528, 2025). "Vascular remodeling normalizes tumor vessels, enhancing adhesion molecule expression like intercellular adhesion molecule 1 (ICAM-1) and vascular cell adhesion molecule 1 (VCAM-1), facilitating immune cell entry and forming high endothelial venules for immune priming." (PMID 41373749, 2025). "A significantly increased accumulation of ICAM‐1–Cy5.5 was observed within the tumor tissues." (PMID 39996528, 2025). "Furthermore, in experiments using ICAM1+ or HER2+ tumor cells treated with ICAM1‐ICG or HER2‐ICG constructs, NIR irradiation consistently induced pyroptosis." (PMID 40539828, 2025). "When expressed on tumor cells, ICAM-1 harbors a pro-tumoral role and promotes metastasis." (PMID 40071851, 2025). "Moreover, cytokines secreted by TAM M2, including TNF-α, ICAM-1, and IL-6, further contribute to tumor growth and invasion." (PMID 40299539, 2025). "The investigation reveals that the combination of ICAM‐1‐Dxd with B7‐H3‐CD3 bispecific antibodies not only demonstrates significant inhibitory effects on tumor growth and metastasis but also plays a vital role in reprogramming the tumor immune microenvironment in triple‐negative breast cancer." (PMID 39996528, 2025). "Although we observed increased ICAM-1 expression in VHL-mutated tumor spheroids, neutralization of ICAM-1 did not impact on the infiltration of NK cells." (PMID 40736709, 2025). "Moreover, ICAM-1 is an effective target for tumor inhibition following CTLA-4 abrogation or CAR-T cells treatment." (PMID 40071851, 2025). "Similarly, the analysis of the global protein profile indicated that the expression of ICAM-1 was increased in PAK4KO tumours." (PMID 40943273, 2025). "The risk score was positively correlated (r > 0.1) with VEGFA, VEGFB, and ICAM1, suggesting enhanced angiogenesis that may restrict immune infiltration and promote tumor progression." (PMID 41293172, 2025). "In a study on cell lines, fibrinogen administration was shown to induce the expression of adhesion molecules such as ICAM-1 and enhance tumour cell migration, as well as increase angiogenesis and vascular endothelial permeability, but further research in NETs is needed." (PMID 41228199, 2025). "Interestingly, while ICAM-1 and VCAM-1 were depleted in presence of Bortezomib, authors concluded loss of E-Selectin alone was necessary to reduce adhesion of tumor cells." (PMID 40071851, 2025). "Adhesion molecules are widely expressed on the surface of immune cells and can assist in the enrichment of nano-photosensitizers encapsulated in immune cell membranes at tumor sites through the interaction with adhesion molecule ligands ICAM-1 on vascular endothelium." (PMID 40284476, 2025).
tumor (continued). "ICAM1 antibody‐bound ICG triggers tumor‐specific, caspase‐1‐independent pyroptosis via CTSS‐mediated GSDMD cleavage, activates antitumor immunity, and synergizes with anti–PD‐1 therapy, offering a non‐apoptotic strategy to overcome resistance in cancer treatment." (PMID 40539828, 2025). "Similarly sized fragments can also activate tumor cell integrins, enhancing binding to intercellular adhesion molecule-1 (ICAM-1)." (PMID 41421148, 2025). "Tumor vessel ICAM-1/VCAM-1 expression decreases by 70%, reducing T cell adhesion efficiency by 85%." (PMID 41415289, 2025). "Additionally, adhesion molecules such as VCAM-1 and ICAM-1 contribute to metastatic progression by mediating tumor–bone interactions." (PMID 41183210, 2025). "In addition, the expression of ICAM-1 at the surface of Ewing’s sarcoma following exposure to pro-inflammatory cytokines improved the recognition and killing of the tumor cells by specific CAR T-cell." (PMID 40071851, 2025). "At the same time, in the RLS40 model, DNase treatment resulted in a decrease in the mRNA levels of pro-tumor phenotype markers (Ccl17, Il10) and an increase in the mRNA levels of anti-tumor phenotype markers (Icam1, Tnfa, Vegfr1), as well as cell mobilization genes (Ern1, Stat3)." (PMID 40867260, 2025). "Additionally, ETS-1 modulates the expression of cell adhesion molecules, such as ICAM-1, which affects the infiltration of immune cells into the tumour microenvironment." (PMID 40181983, 2025). "Metastatic progression further relies on NF-κB-mediated induction of cell adhesion molecules, such as vascular cell adhesion molecule-1 (VCAM-1), endothelial leukocyte adhesion molecule (ELAM-1), and ICAM-1, which facilitate the tumor cell‒endothelial interactions critical for extravasation." (PMID 40562870, 2025). "Additionally, GSN effectively inhibited tumor cell adhesion activity and the expression of intercellular adhesion molecule-1 (ICAM-1)." (PMID 38910887, 2024). "Furthermore, we elucidated the key biological mechanisms that how DAC can work in synergy with ICAM1‐ADC by remodeling tumor microenvironments (TME)." (PMID 38874532, 2024). "ICAM-1 is regarded as an important mediator in tumor migration and invasion." (PMID 38258133, 2024). "In addition to the well-known angiogenic effects of activated CXCL8, it also enhances the expression of ICAM1 in the context, which aids tumour cell adhesion to endothelial cells and liver metastasis." (PMID 39025845, 2024). "Of note, ICAM1 was dominantly enriched among LUAD and LUSC tumor cells in addition to several alveolar cells, endothelial cells and some macrophages, suggesting the leading functions of tumorous ICAM-1 in regulating NSCLC progression." (PMID 39168965, 2024). "Moreover, in the tumor area, the RT upregulates the adhesion molecules (including ICAM-1 and VCAM-1), which are also expressed in blood vessels that predispose to immune cell infiltration of the tumor microenvironment." (PMID 38203748, 2024). "Recent studies have revealed the roles of FG and ICAM-1 in orchestrating the immune-cancer cycle, including regulating immune cell effector functions during inflammation, as well as manipulating cancer cell metastasis and tumor angiogenesis." (PMID 39168965, 2024). "The results revealed that, even in the presence of IFN-γ, treatment with aT-sEVs could still decrease the levels of membrane PD-L1, MHC-I and ICAM-1 on tumour cells." (PMID 38719909, 2024). "Regarding prognosis, it has been reported that ICAM-1 participates in leukocyte adhesion, motility, and immunological activation in tumor immunity, and immunotherapy may enhance the prognosis of patients at high risk." (PMID 38799250, 2024). "Indeed, recent studies highlight the significance of LFA-1 expression in forming the IS in T and NK cells and the importance of the LFA-1/ICAM-1 axis in CAR-T cell/tumor cell interactions in solid tumors." (PMID 38779672, 2024).
tumor (continued). "Additionally, tumor tissue analysis revealed a significant decrease in ICAM1, MMP9 and MUC1 expression following atorvastatin treatment, along with inhibited MAPK pathway activation." (PMID 38907234, 2024). "ICAM-1 can impact tumor development by promoting adhesive between tumor and immune cells." (PMID 38361933, 2024). "However, following statin treatment, there was a significant decrease in the expression ICAM1 and the presence of neutrophils in tumor tissues, consistent with the findings observed in the TNBC mouse model." (PMID 38907234, 2024). "Additionally, we discovered that atorvastatin effectively inhibited ICAM1 expression in tumor cells." (PMID 38907234, 2024). "Another suitable approach could be to express an anti-ICAM-1 scFv on the CAR-T that would interact with ICAM-1 in the tumor cell." (PMID 38779672, 2024). "When in touch with T cells, ICAM-1 can change the growth and development of tumor cells." (PMID 38799250, 2024). "HDAC inhibitors not only exhibit anti-angiogenic properties across various cancer types but also enhance leukocyte adherence and movement within tumor vessels, primarily through the upregulation of ICAM-1, underscoring their potential to boost the effectiveness of immunotherapy." (PMID 38580870, 2024). "Only a small percentage of cells in Huh7 and Hep3B cell population were ICAM-1-positive, but importantly, the ICAM-1-positive subpopulation expressed higher levels of genes for tumor stemness, including Sox3 and Oct4, and made more hepatospheres in in vitro assays." (PMID 38786066, 2024). "Additionally, in a murine model of breast cancer, ICAM-2 upregulation in dendritic cell vaccine therapy correlated with improved tumor control, which interestingly exhibited lower ICAM-1 expression." (PMID 38786066, 2024). "Therefore, ICAM1 expressed on tumor cells plays a pivotal role in coordinating antitumor immune responses, particularly adaptive immune responses." (PMID 39802954, 2024). "ICAM-1 plays a crucial role in facilitating the adhesion of immune cells to the tumour site, and its reduced expression can hinder the recruitment and activation of antitumour immune cells, thereby allowing the tumour to evade immune surveillance and continue to progress." (PMID 39456639, 2024). "In BAP1-mutated UM, researchers found that ITGB2-ICAM1 signaling was enhanced between terminally exhausted CD8+ T cells and GDF15hiATF3hiCDKN1Ahi tumor cells, and inhibiting either ICAM1 or ITGB2 could prevent liver metastasis in the BAP1-mutated patients." (PMID 38966635, 2024). "Tumor endothelial cells fail to express proper ICAM-1 and VCAM-1 levels." (PMID 38576482, 2024). "Furthermore, in a co-culture system of tumor cells and neutrophils, antagonizing ICAM1 resulted in a significant reduction in the number of neutrophils adhering to the tumor cells." (PMID 38907234, 2024). "Moreover, this IFN-γ also triggers the upregulation of intracellular adhesion molecule 1 (ICAM-1) in tumor cells, facilitating the adhesion and infiltration of eosinophils into the tumor microenvironment." (PMID 38892286, 2024). "Notably, ICAM-1 OE OT-I CD8+ T cells maintained ICAM-1 overexpression during coculture and exhibited increased tumor-killing capacity, degranulation, and activation." (PMID 38169608, 2024). "Therefore, the premise for tumor metastasis through ICAM-1/VCAM-1–mediated myeloid cell–CTC clustering is such that the myeloid cell–CTC interaction should be permissive." (PMID 38786066, 2024). "Interestingly, these TINs were predominantly located around tumor cells exhibiting high ICAM1 expression." (PMID 38907234, 2024). "ICAM-1–β2 interaction also allows tumor cells to adhere to leukocytes, which facilitates the subsequent tumor metastatic process via promoting tumor cell extravasation from vascular endothelium and triggering intracellular signaling to support tumor cell proliferation and migration." (PMID 39168965, 2024).
tumor (continued). "Exogenous Icam-1 may originate from tumor cell membrane detachment or be secreted into the extracellular matrix in vesicle form." (PMID 38463490, 2024). "Whether NMT-1 can prolong ICAM-1-mediated adhesion for longer in secondary tumours remains to be investigated." (PMID 38391953, 2024). "Moreover, the expression of ICAM-1 in whole tumor tissues was significantly reduced upon treatment with FTY720 (P <0.05)." (PMID 38169608, 2024). "Tumor ICAM-1 and VCAM-1 are a modality for tumor dissemination." (PMID 38786066, 2024). "This study demonstrated ICAM-1 is a strong indicator of tumor stemness and metastasis, although it remains undecided whether ICAM-1 is merely a coincidental marker for tumor stemness or ICAM-1 on tumors has direct functions for metastasis." (PMID 38786066, 2024). "Furthermore, ICAM-1 expression, a marker for activated endothelium, strongly correlated with the frequency of M1-like macrophages and T cells in the tumor microenvironment." (PMID 39286984, 2024). "According to our RNA-seq data, in addition to CDH1/CDH2 (E-cadherin/N-cadherin), ICAM1 was upregulated in both T1M1 PDAC tissues and MET-containing CM-treated PDAC cells, which indicated that METs may affect tumour cell adhesion through ICAM1." (PMID 39025845, 2024). "miR-335-5p targets the 3’-UTR and decreases expression of intercellular adhesion molecule 1 (ICAM‐1) mRNA, an oncogene protein that drives the metastasis of tumour cells by recruiting inflammatory cells and promoting the proliferation, angiogenesis and invasion of cancer cells." (PMID 39187514, 2024). "Furthermore, targeting ICAM-1 along with an anti-PD1 antibody has resulted in rapid tumor clearance and prolonged survival in a mouse model of advanced thyroid cancer." (PMID 39596815, 2024). "Furthermore, compared with the splenic CD8+ T cells, tumor CD8+ T cells exhibited markedly increased ICAM-1 expression." (PMID 38169608, 2024). "Collectively, the findings of this study indicate that monitoring tumor infiltration by ICAM-1+CD8+ T cells using ICAM-1-targeted noninvasive imaging provides a novel means to develop effective RT combination therapies and increases the frequency of the abscopal effect in clinical settings." (PMID 38169608, 2024). "Vascular endothelial growth factor (VEGF) and fibroblast growth factor 2 (FGF2) secreted by tumor cells induce tumor endothelial cells anergy by inhibiting the upregulation of ICAM-1, VCAM-1, and selectins on tumor endothelial cells under inflammatory stimulation." (PMID 39325128, 2024). "IL-1B from osteoblasts has been shown to facilitate adhesion of circulating tumour cells to sinusoidal endothelial cells by increasing the expression of vascular cell adhesion molecules such as intercellular adhesion molecule 1 (ICAM-1), vascular cell adhesion molecule 1 (VCAM-1), and E-selectin." (PMID 38800348, 2024). "This expression of ICAM-1 in tumor cells is more prominent in the center of the tumor and in front of invasion, which could explain why eosinophils tend to concentrate in those areas." (PMID 38892286, 2024). "Interestingly, circulating tumor cells can upregulate ICAM-1 or VCAM-1 expression to recruit and retain myeloid cells on them and utilize those immune cells for metastasis." (PMID 38786066, 2024). "On the other hand, TECs also might contribute to lymphocyte migration into the tumor via ICAM1/ICAM2-(ITGAL + ITGB2) interactions with T/NK cells." (PMID 39093451, 2024). "Upregulated ICAM‐1 expression required the activation of PLCβ via tyrosine kinase to induce PKCα and c‐Src, allowing the transcriptional factors to bind on the AP‐1 promoter binding sites for tumour cell motility." (PMID 37082943, 2023). "We also suggest that intercellular adhesion molecule 1 (ICAM-1)—and potentially other molecules—may compensate for loss of CD44 in other tumor relevant processes." (PMID 37174657, 2023). "LFA-1/ICAM-1 also disrupts CD8 + T cells recirculation by promoting tumor tissues aggregation." (PMID 36895477, 2023).
tumor (continued). "Other crucial elements associated with poor CAR-T cell trafficking and infiltration in solid tumors, are the abnormal secretion of vascular-related factors such as intercellular adhesion molecule 1 (ICAM-1) as well as the presence of other immune cells in tumor tissue." (PMID 36564524, 2023). "Furthermore, co-culture of PD-1high hHER2-CAR-T cells with hHER2-B16 or hHER2-E0771 upregulated ICAM-1 expression on the target tumor cells to a level similar to that on B16 cells treated with recombinant IFNγ alone." (PMID 37388744, 2023). "On the other hand, exosomes released by tumor cells have adhesion proteins such as ICAM-1 on their surfaces, which can bind to LFA-1 on the surface of CD8+ T cells and promote the interaction between tumor cell-derived exosomes and CD8+ T cells, leading to immune escape." (PMID 37670933, 2023). "Moreover, Yap enrichment on Icam1 loci progressively increased with time following tumor implantation." (PMID 36921037, 2023). "So, the tumor suppressing and encouraging functions of NF-κB manifest a curiosity wherein the activities of Toll like receptors (TLRs), intercellular adhesion molecule 1 (ICAM-1) and lymphotoxin beta (LTB) assume significance." (PMID 37970206, 2023). "More specifically for GC, while EpCAM-CAR T cells alone reduced or eliminated tumor burden but were susceptible to relapse, bispecific CAR T cells targeting EpCAM and ICAM-1 significantly prevented relapse and decreased tumor size in gastric, lung, breast, and pancreatic cancer." (PMID 38067366, 2023). "It was recently demonstrated that culturing of activated murine CD8+ T-cells on a “Synthetic Immune Niche” (SIN), consisting of immobilized CCL21 and ICAM-1, enhances T-cell expansion, increases their cytotoxicity against cultured cancer cells and suppresses tumor growth in vivo." (PMID 36937426, 2023). "To evaluate the contribution of integrin-mediated cell adhesion to T-ALL progression after tumor establishment, we administered an anti-ICAM-1 blocking antibody alone or in combination with an anti-VCAM-1 blocking antibody after LN3 leukemic burden reached 1–8% in the spleen." (PMID 37805579, 2023). "ICAM1 promotes tumor cell stemness and transendothelial migration." (PMID 36632469, 2023). "We next tested whether the integrin ligands ICAM-1 and VCAM-1 were expressed by tumor-associated myeloid subsets, with a particular interest in macrophages, monocytes, and cDC2s, the myeloid cell types we previously found promote T-ALL survival." (PMID 37805579, 2023). "Moreover, our work describes the contrasting role of soluble and membrane-bound ICAM-1 in regulating tumor cell killing." (PMID 37732732, 2023). "First, we examined whether ICAM‐1 in cancer cells might regulate the anti‐tumor activity of CD8+ T cells." (PMID 37097643, 2023). "In contrast, ICAM1 re-expression restored the tumor cell adhesion ability of CAR-T." (PMID 38115906, 2023). "Novel tumour markers are also emerging which could be harnessed for PC diagnosis including ICAM-1, aiming to improve upon current biomarkers including CA19-9." (PMID 37006185, 2023). "Inside the tumor region, ICAM1 enhanced T-cell adhesion and interaction with tumor cells." (PMID 36871040, 2023). "Importantly, recent studies have demonstrated that the adhesion between CAR-T cells and target cancer cells is directly regulated by IFNγ, which induces an upregulation of ICAM-1 on target tumor cells, promoting the formation of conjugations with CAR-T cells." (PMID 37388744, 2023). "Tumor endothelial cells (ECs) promote the adhesion of tumor cells to vascular ECs and inhibit the infiltration of T cells into the tumor bed by modulating CAMs (ICAM‐1 and VCAM‐1)." (PMID 37638340, 2023). "We next evaluated the in vivo efficacy of two ICAM1 ADCs using the same CCA tumor xenograft model." (PMID 37717087, 2023). "Furthermore, differential expression of the cell adhesion pathway gene ICAM1 in solid tumors affects CAR-T tumor killing capacity." (PMID 38115906, 2023).